LGR5 (leucine rich repeat containing G protein-coupled receptor 5)
Diseases named in the same sentence as LGR5 in open-access papers (continued):
Sharing a sentence is not in itself a finding about the gene and the disease.
breast cancer (continued). "Recently, a few studies have reported that the ginsenosides Rh2 and Rg3 could inhibit CSC properties in skin squamous cell carcinoma and breast cancer through reducing the number of Lgr5-positive cells or regulating self-renewal activity, respectively." (PMID 32650569, 2020). "While it may be tempting to speculate on the role of STAT3 in LGR5 expression in mammary stem cells and breast cancer stem cell development given the interplay between NFKB and STAT3 signalling, this however requires further experimental evidence." (PMID 32331320, 2020). "An IHC study by Hou demonstrated LGR5 and β-catenin expression in 126 breast cancer patients." (PMID 31814939, 2019). "As EMT is commonly involved in cell mobility changes, and LGR5 has been identified as involved in EMT progression in breast cancer 22 and hepatocellular carcinoma 27, we investigated the expression of EMT markers and EMT‐related transcription factors by Western blotting." (PMID 29777575, 2018). "A previous study showed that LGR5 is involved in breast cancer progression." (PMID 29777575, 2018). "Moreover, Kaplan-Meier analysis of LGR5 together with β-catenin expression revealed that breast cancer patients with high simultaneous expression of tumor LGR5 and β-catenin expression had the worst prognosis (p = 0.027)." (PMID 29471794, 2018). "If the data from this mouse model can be extrapolated to human basal-like breast cancers, we question whether inhibiting Lgr5 function will be able to significantly impact the clinical course of these cancers." (PMID 28649656, 2017). "Importantly, our data conclusively demonstrate that Lgr5 is dispensable for both fetal and adult mammary stem cell activity and for the development of mammary tumors." (PMID 28649656, 2017). "Yet, even though Lgr5 expression marks a population of fetal mammary stem cells, the protein is not required for stem cell activity or for tumors to form in a mouse model of breast cancer." (PMID 28649656, 2017). "Interestingly, the expression of Pik3caH1047R in basal Lgr5 + and luminal Krt8 + cells induced mammary tumors of distinct histotypes on average after 108 and 78 days, respectively, indicating that aggressiveness and latency greatly depend on the identity of the cell-of-origin." (PMID 40676433, 2025). "Importantly, numerous studies using genetic lineage tracing analysis or detection by antibodies against Lgr5 have indicated Lgr5 as biomarkers of cancer stem cells of various human cancer types, such as adenocarcinoma, glioblastoma, and colorectal and breast cancers." (PMID 31358061, 2019). "Notably, Lgr5 is required for the maintenance of breast cancer stem cells." (PMID 31358061, 2019). "Therefore, LGR5 is a likely therapeutic target in breast cancer patients." (PMID 29471794, 2018). "Anti-LGR5-ADC effectively inhibited tumor growth in MDA-MB231 and patient-derived xenografts with high-LGR5 in breast cancer." (PMID 39821694, 2025). "And LGR5 knockdown reduced tumor invasion and migration and blocked EMT by inhibiting the Wnt/β-catenin pathway, in both breast cancer and glioma." (PMID 37328854, 2023). "Studies have shown that LGR5 promotes EMT by activating the Wnt/β-catenin pathway, which promotes the invasion and migration of breast cancer, glioma stem cells, and a variety of other malignant tumors." (PMID 36288272, 2022). "However, the mechanism by which LGR5 may promote breast cancer is not fully understood." (PMID 29471794, 2018). "Furthermore, LGR5 was highly expressed in HepG2, Hep3B and Huh7 cells, while weakly expressed in siHa cervical cancer, PC3 prostate cancer, A549 lung cancer and MCF-7 breast cancer cell lines." (PMID 31717443, 2019). "Our data further demonstrate that functional Lgr5 is not necessary for tumorigenesis in an SV40 T-antigen-driven mammary cancer model." (PMID 28649656, 2017).
breast cancer (continued). "To investigate the involvement of lgr5 DNA methylation in CSC differentiation, we derived cancer stem or stem-like cells from HCT116 cell line following a spheres model as described where breast cancer stem cells were enriched by culturing in suspension as nonadherent spheres." (PMID 26599100, 2015).
intestinal tumors (41 papers, 2010 to 2025). "Compared to the control group, the protein levels of CD133 and Lgr5 were significantly reduced in Prrc2a‐deficient intestinal tumors." (PMID 39582289, 2025). "IPA analysis of 270 mutated genes shared by DMBA, MUN, and PhIP treatment with PP2A deficiency in Lgr5+ cells revealed 10 top significantly enriched pathways, including the intestinal tumor metastasis signaling (p-value = 2.12 × 10−57) and Wnt/beta-catenin signaling (p-value = 1.40 × 10−55)." (PMID 31905853, 2019). "Thus, there is compelling evidence in both human and murine intestinal tumors that LGR5+ stem cells contribute to cancer initiation and progression and that high LGR5 expression is associated with worse clinical outcomes." (PMID 23596566, 2013). "DCLK1+Lgr5+ cells can be identified in intestinal tumours that arose following activation of Wnt signaling in Lgr5+ stem cells, and a recent study confirmed DCLK1 as a downstream target of Wnt signaling." (PMID 36263033, 2022). "(A, C) Representative section of Apc mutant intestinal tumours analysed by single-molecule fluorescence in situ hybridisation (smFISH) for Thbs1 (pThbs1, red dots) and Lgr5 (pLgr5, green dots in A) or the YAP target Sca1 (pSca1, green dots in C)." (PMID 35543624, 2022). "After Abhd5 knockout, intestinal tumours showed a significant increase in the number of Lgr5-GFP-positive cells, characterized as CSCs." (PMID 34795238, 2021). "The expression of a stabilized oncogenic form of β-catenin in Lgr5+ stem cells produced intestinal tumors with a high expression of intestinal stem cell genes." (PMID 33349639, 2020). "This is also observed in LGR5+ cells in primary intestinal tumours in mice and human colorectal tumours." (PMID 31906589, 2020). "For this, we induced intestinal tumors using the stem cell marker locus Lgr5 to confer bi‐allelic Apc deletion following tamoxifen treatment of Lgr5CreERT2; Apcflox mice." (PMID 30885958, 2019). "Since the discovery of specific ISC populations, including Lgr5+, Bmi1+, or Lrig1+ ISCs, and their ability to serve as the origin of intestinal tumor development, much interest has been focused on their function in the context of diet and aging." (PMID 29904634, 2018). "We found that Dll4 is expressed near the Lgr5+ stem cells also in the intestinal tumors, therefore indicating a possible role of this ligand in the maintenance of also the tumor stem cells." (PMID 28086833, 2017). "The results of this study show that all types of intestinal tumors contain Bmi1- or Lgr5-positive cells, which clonally expand to contribute to tumor propagation." (PMID 28176811, 2017). "Compared with the controls, Lgr5 protein and gene expression was reduced in the small and large intestinal tumors from both mutants, but mostly in those from ubiqDll4-/- mice." (PMID 28086833, 2017). "Our observations suggested the Lgr5+ cell located at the crypt base as cell-of-origin of intestine tumors, and the shorter crypts in tumors compared with normal tissues indicated that they had proliferated via crypt fission." (PMID 28176811, 2017). "Notwithstanding, the role of Lgr5 in CRC remains indistinct; while some studies suggest that intestinal tumors arise from Lgr5-positive cells, Walker and colleagues showed that suppression of Lgr5 expression enhances tumorigenesis." (PMID 28209178, 2017). "The differences between the two types of Dll4 mutants in the expression of Lgr5 and Bmi1 markers in the small and large intestinal tumors were statistically significant." (PMID 28086833, 2017). "Mouse LGR5- positive cells give rise to intestinal tumors with higher efficiency than other intestinal cell populations upon mutational activation of the Wnt pathway." (PMID 24133453, 2013). "Significantly, Lgr5+ ISC have also recently been identified as both the cells of origin for murine intestinal tumors and tumor-maintaining cancer stem cells in established adenomas." (PMID 23596566, 2013).
intestinal tumors (continued). "One intriguing and unexpected finding in the present study is the demonstration of MCHR1 expression in LGR5-positive crypt stem cells, which are considered to play a key role in the development of intestinal tumors." (PMID 22848656, 2012). "Nevertheless, our findings are in line with current studies, identifying LGR5 expressing cells as the cells of origin in intestinal tumours." (PMID 22530031, 2012). "Quantitative RT-PCR analysis of the isolated tumors showed that expression of the WNT target genes and stem cell markers Lgr5, Ascl2, and Axin2 were suppressed in the Usp7 cKO tumors, suggesting that Usp7 depletion inhibits WNT signaling in the Apc-deficient intestinal tumors." (PMID 36669491, 2023). "This strongly argues that intestinal tumors might be initiated in both Lgr5+ stem cells and Lgr5− TA cells." (PMID 37746286, 2023). "In support of this, it is noteworthy that BMI1+ cells appear independent of the Wnt pathway for their proliferation in contrast to LGR5+ cells, while BMI1+ and LGR5+ cells have been shown to represent distinct populations of cancer stem cells in intestinal neoplasms." (PMID 37048132, 2023). "CSCs isolated from human intestinal tumor specimens express the Lgr5 crypt marker." (PMID 31905853, 2019). "While previous studies suggested that intestinal tumors arise from LGR5-positive cells." (PMID 26745821, 2016). "Therefore, given the observed reduction in the ApcMin/+ small and large intestinal tumor number in the Dll4 knock-out mice compared with the controls, we decided to analyse if Dll4 reduction was affecting the Lgr5+ and/or Bmi1+ stem cell expression in the tumors." (PMID 28086833, 2017). "In intestinal tumours, DCLK1 often co-expresses with LGR5 at crypt base and DCLK1+LGR5+ stem cells are able to continuously produce tumour progeny under the APC+/− mice." (PMID 28195176, 2017). "In addition, as we only analysed the Lgr5 and Bmi1 positive stem cell populations, it is not certain if this pathway can affect similarly all the stem cells present in the intestinal tumors." (PMID 28086833, 2017).
hepatocellular carcinoma (40 papers, 2011 to 2026). A malignant tumor that arises from hepatocytes. "Significantly, Lgr5 is among the highest upregulated genes in hepatocellular carcinoma associated with mutations in the Wnt/β-catenin pathway." (PMID 33767594, 2021). "In the current study, the function of long noncoding RNA (LncRNA) RAB5IF was elucidated in hepatocellular carcinoma (HCCs) in association with LGR5 related signaling." (PMID 31717443, 2019). "PTEN deficiency also promotes the development of hepatocellular carcinoma 37, 38, suggesting that the abnormal proliferation of Lgr5+ hepatocytes triggered by AKT/β-catenin signaling may be a factor leading to liver cancer." (PMID 33767594, 2021). "Thus, it is clear that the genes argsyn, ScarF2, LGR5, and rasgbd are probably associated with liver pathological process, including glycolipid metabolism disorder, hepatocellular carcinoma, and autophagy." (PMID 29670865, 2018). "Accordingly, in hepatoma cells (HepG2), a hypoxic condition triggers LGR5 expression, supporting that the LGR5-β-catenin linkage is controlled by oxygen gradient within the liver acinus." (PMID 41226735, 2025). "LGR5 overexpression in hepatocellular carcinoma cells resulted in changes from a mesenchymal phenotype to a more aggregated phenotype typical for the epithelial subtype." (PMID 37770230, 2023). "High expression of LGR5 is reported in human colorectal adenomas and cancers, hepatocellular carcinoma, and basal cell carcinoma." (PMID 36428626, 2022). "In LGR5-positive hepatocellular carcinoma, LGR5 and LSD1 appeared to enhance each other's expression, maintaining the stem cell characteristics of carcinoma cells." (PMID 34082769, 2021). "Here, we report the enrichment of LGR5 expressing cells, a well-recognized stem cell marker, in mouse liver tumors, and the upregulation of LGR5 expression in human hepatocellular carcinoma." (PMID 32327656, 2020). "According to this finding, for hepatocellular carcinoma it was reported that LGR5 promotes metastasis through inducting EMT." (PMID 30770730, 2019). "Taken together, these findings for the first time demonstrate novel evidence that LncRNA RAB5IF promotes the growth of hepatocellular carcinoma cells via upregulation of LGR5 mediated β-catenin and c-Myc signaling axis as a potent oncogenic target." (PMID 31717443, 2019). "Here, we investigated LGR-5 expression using immunohistochemistry and analyzed the correlation between clinical features and prognosis in patients with hepatocellular carcinoma (HCC)." (PMID 31126119, 2019). "Recently, Lgr5 has been found to induce epithelial-mesenchymal transition (EMT) in human hepatocellular carcinoma cells and inhibit their apoptosis, resulting in drug resistance." (PMID 31754399, 2019). "Overall, these findings provide novel evidence that LncRNA RAB5IF promotes the growth of hepatocellular carcinoma cells via LGR5 mediated β-catenin and c-Myc signaling as a potent oncogenic target." (PMID 31717443, 2019). "Taken together, these findings for the first time demonstrate novel evidence that LncRNA RAB5IF promotes the growth hepatocellular carcinoma cells via upregulation of LGR5 mediated β-catenin and c-Myc signaling axis as a potent oncogenic target." (PMID 31717443, 2019). "LGR5 protein was also shown to regulate epithelial cell phenotype and the survival of hepatocellular carcinoma cells." (PMID 29670865, 2018). "We previously demonstrated that sustained HCV replicon expression in hepatoma cell lines is directly linked to the gain of cancer stem cell (CSC)-like properties and overexpression of CSC markers (DCLK1, Lgr5, CD133, c-Myc)." (PMID 25948779, 2015).
hepatocellular carcinoma (continued). "When compared to corresponding normal tissues, LGR5/GPR49 mRNA is overexpressed in human hepatocellular carcinomas, basal cell carcinoma, colon-, colorectal- and ovarian tumors." (PMID 21978106, 2011). "In hepatocellular carcinoma, LGR5 overexpression identifies a distinct subgroup that may inform precise staging and treatment decisions." (PMID 41194856, 2025). "GPR49, also known as Lgr5, that plays a critical role in various cancers, including basal cell carcinoma, head and neck squamous cell carcinoma, oral squamous cell carcinoma, and hepatocellular carcinoma." (PMID 38895631, 2024). "Notably, Lgr5 has been demonstrated upregulated in various cancer tissues, such as basal cell carcinomas, hepatocellular carcinomas, colorectal tumors, and ovarian tumors." (PMID 31358061, 2019). "Notably, the expression of Lgr5 is reported to be increased in human colorectal adenomas and cancers, hepatocellular carcinoma, basal cell carcinoma, and neuroblastoma." (PMID 31358061, 2019). "In hepatocellular carcinoma (HCC), LGR5 marks a distinct tumor cell subpopulation with stem-like properties, contributing to tumor progression and metastasis, and has been proposed as a potential biomarker for precise staging." (PMID 41194856, 2025). "However, studies on LGR-5 expression in human hepatic carcinoma are scarce." (PMID 31126119, 2019). "The purpose of the present study was to investigate the prognostic value of Leucine-rich repeat-containing G-protein coupled receptor 5 (LGR5) in hepatocellular carcinoma (HCC) and its role in promoting HCC metastasis." (PMID 28881613, 2017). "Next, we queried the TCGA liver carcinoma database to examine the expression of AXIN2 and LGR5 in HCC patient samples." (PMID 41550750, 2026). "High LGR5 expression enhanced tumor proliferation through WNT/β-catenin in lung, gastric, CRC, hepatocellular carcinoma (HCC), breast, cervical, endometrial, oesophageal, bone, and brain cancers." (PMID 39821694, 2025). "It was found that the growth of Lgr5+ cells can be controlled by PTEN/AKT and Wnt/β-catenin pathways, and Lgr5 has emerged as a potential therapeutic target for the treatment of hepatocellular carcinoma." (PMID 40003899, 2025). "In addition, STRAP knockout in hepatocellular carcinoma decreased mRNA abundance of stemness markers and liver progenitor genes, including AXIN2, LGR5, CD133, and CD44." (PMID 34206917, 2021).